TNF (tumor necrosis factor)
Diseases named in the same sentence as TNF in open-access papers (continued):
Sharing a sentence is not in itself a finding about the gene and the disease.
depression (continued). "In rats with CSVD and depression, PY significantly increased body weight; alleviated depression-like behaviors; and decreased the levels of inflammatory cytokines such as TNF-α, IL-1β, and IL-6 in both serum and hippocampus." (PMID 40584618, 2025). "Elevated levels of pro-inflammatory cytokines such as IL-6 and TNF-α in major depressive disorder (MDD) further skew bone remodeling toward resorption." (PMID 41007423, 2025). "Previous research has shown also that TNF-α and IL-1β disruption affects depression by hindering serotonin production and signaling, a crucial neurotransmitter for mood regulation." (PMID 39902492, 2025). "Contributing factors include chronic pain, stiffness, elevated IL-6 and TNF-α, depression, anxiety, and medication side effects." (PMID 41153815, 2025). "Its root extract suppresses the expression of inflammation-related proteins such as cyclooxygenase-2, iNOS, IL-6, IL-1β, and TNF-α, while modulating neuroendocrine and neurotransmitter systems to exert neuroprotective effects in mouse models of depression." (PMID 40936908, 2025). "In a study of adolescents with depression, the content of Bifidobacterium in the gut microbiota of subjects was negatively correlated with the level of TNF-α." (PMID 40771678, 2025). "A meta-analysis showed that higher concentrations of TNF-α, IFN-γ, IL-6 and IL-10 were significantly associated with higher levels of depression in individuals with MS (r = 0.35, 95% CI [0.6,0.03], p = .015." (PMID 39867847, 2025). "In a model of depression, zileuton significantly improved depressive‐like behavior by suppressing hippocampal TNF α, IL-1β, nuclear NF-κB p65 and microglial activation, reducing neuronal apoptosis and restoring synaptic proteins and neurogenesis." (PMID 40538546, 2025). "Another randomized, double-blind control study showed a decrease in IL-6 and tumor necrosis factor-alpha (TNF-α) levels just after 40 min and was correlated with a lower Montgomery-Asberg Depression Rating Scale (MADRS) score." (PMID 40806626, 2025). "Chronic stress accelerates dementia onset in depression via cytokines, with elevated interleukin-6 and tumor necrosis factor-α levels observed in the serum, cerebrospinal fluid, and prefrontal cortices of depressed patients." (PMID 39981405, 2025). "This stands in line with information from Smith’s macrophage theory of depression in which he identified, in addition to il-1β, IFN-α, and TNF-α among the main substances that can provoke and influence the course of depression." (PMID 40004649, 2025). "The degree of psychopathological changes in patients with schizophrenia or depression was linked with the levels of the following pro-inflammatory cytokines: IFN-α, IFN-γ, IL-1β, IL-6, and TNF-α." (PMID 41010622, 2025). "The aim of our study was to explore the correlation between cytokines TNF-α and IL-6, disease activity, and the degree of depression in patients with RA." (PMID 40699818, 2025). "Stress increases inflammatory cytokines (TNF-α, IL-1β, and IL-6), which disrupt neurotransmitter levels (serotonin, dopamine, and norepinephrine), contributing to disorders such as anxiety, depression, and neuroinflammation." (PMID 40309824, 2025). "Depression score and the serum concentrations of TNF-α, IL-6, and hs-CRP were decreased after intervention in the omega-3 fatty acids group compared with the placebo group." (PMID 39997208, 2025). "Peripheral administration of TNFα antagonist has been shown to improve depressive mood, reduce fatigue and alleviate depression." (PMID 40352929, 2025). "Although TNF-α inhibition (e.g., with infliximab) has shown efficacy in animal models, its utility as monotherapy for human depression remains limited." (PMID 41000397, 2025). "Depression score and the serum concentrations of tumor necrosis factor-α (TNF-α), interleukin-6 (IL-6), and high-sensitivity C-reactive protein (hs-CRP) were assessed before and after the study." (PMID 39997208, 2025).
depression (continued). "Studies have found the levels of IL-6, NF-κB, TNFα and IL-1β were increased in the blood and brain tissue with depression." (PMID 40308754, 2025). "Some anti-TNF drugs, such as infliximab and etanercept, have been reported to decrease depressive symptoms, especially for patients with depression with higher CRP levels at baseline." (PMID 40699818, 2025). "Both preclinical and clinical studies have found higher levels of IL-1β, TNF-α, and IL-6 in peripheral blood and brain tissue of patients with depression." (PMID 41561993, 2025). "Increased evidence points to the number of immune-related genes, such as IL1B, IL6, and TNF, that connect epilepsy and depression through inflammatory pathways." (PMID 40941042, 2025). "Further statistical linear regression analysis shows that IL-6 (B = 0.171, p = 0.000) and TNF-α (B = 0.039, p = 0.012) are statistically significant predictors (p < 0.05) of depression intensity on the Hamilton depression scale in group I." (PMID 40699818, 2025). "Review of the literature on the roles and therapeutic applications of TNF-α in major depressive disorder." (PMID 40313235, 2025). "Pro-inflammatory cytokines that are involved in the pathogenesis of RA and PsA, including TNF-α, IL-1 and IL-6, are also elevated in patients with a depression or anxiety disorder." (PMID 39504461, 2025). "Studies have consistently found that individuals with depression often exhibit elevated levels of inflammatory markers in their blood and cerebrospinal fluid, including cytokines such as IL-1β, IL-6, and TNF." (PMID 40065395, 2025). "Another study published in 2020 revealed that the serum TNF-a levels were higher in patients with severe depression than in healthy controls." (PMID 39860505, 2025). "For instance, the tumor necrosis factor-alpha (TNF-α) inhibitor infliximab has been shown to have antidepressant effects in treatment-resistant depression, particularly in patients with elevated levels of C-reactive protein (CRP)." (PMID 40004109, 2025). "Studies have reported significant reductions in anxiety and depression symptoms following anti-TNF therapy, likely due to the reduction in inflammation and improvement in disease control." (PMID 40823034, 2025). "Increased levels of depression-related pro-inflammatory cytokines (such as TNF-α, IL-6, and IL-1) can activate the hypothalamic-pituitary-adrenal (HPA) axis and the sympathetic nervous system via various pathways." (PMID 40270731, 2025). "A grouped meta-analysis found significant positive associations between concentrations of TNF-a, IFN-γ, IFN-γ PHA, IL-10, IL-10 (LPS and PHA), IL-6, IL-6 (LPS and PHA) and levels of depression in individuals with MS." (PMID 39867847, 2025). "Pro-inflammatory cytokines levels, such as IL-1, IL-6, and tumor necrosis factor (TNF) -α, were significantly raised in depression patients compared with normal subjects 35,36." (PMID 40520890, 2025). "Many patients with depression show increased levels of inflammatory cytokines, including TNF-α and interleukin (IL)-6." (PMID 40284791, 2025). "When ZEA 50 mg/kg was administered for 14 days, the levels of TNF-α and IL-1β in the hippocampus and subsided depression and anxiety symptoms were lowered." (PMID 40292259, 2025). "The pharmacological inhibition of EZH2 or upregulation of claudin-5 restored BBB integrity and reduced TNF-α levels in the brain, mitigating depression-like behaviors." (PMID 40331982, 2025). "Neuroinflammation has emerged as a core feature of many psychiatric disorders, particularly schizophrenia and depression, where pro-inflammatory cytokines such as IL-6, TNF-alpha, and C-reactive protein are persistently elevated." (PMID 40218925, 2025). "Markers of inflammation or immune activation (including TNFα, CRP, IL-6) are closely associated with depression and sleep quality." (PMID 40313235, 2025).
depression (continued). "Concurrently, these metabolic shifts enhance systemic inflammation by amplifying IL-6 and TNF-α release, priming microglia, and compromising the BBB integrity, mechanisms long implicated in depression and other affective disorders." (PMID 41244880, 2025). "Exploratory analyses in combined groups showed that measures of past drinking, AUD severity, and anxiety/depression positively correlated with IL‐18 and TNF‐α and negatively correlated with BDNF." (PMID 40317574, 2025). "In a similar investigation of depression, researchers correlated baseline levels of inflammatory markers (CRP, interleukins, TNF) with the severity of depression and compared their values in response to therapy." (PMID 40431406, 2025). "The presented results show that IL-8 and TNF-alpha correlate with reward-dependence in people with depression." (PMID 40002454, 2025). "This study confirmed that the levels of IL-6 and TNF-α in patients with depression significantly decreased before and after sertraline monotherapy." (PMID 41023687, 2025). "Several cytokines including Interleukin 6 (IL6), C-reactive protein (CRP) and Tumor Necrosis Factor alpha (TNFα) have elevated levels in depression." (PMID 40352929, 2025). "Meta-analyses indicated an increase of inflammatory biomarkers such as IL-6, IL-18 in depression but regarding TNF-α there were inconsistent reports." (PMID 39717874, 2025). "Exercise also has anti-inflammatory effects, lowering levels of pro-inflammatory cytokines such as IL-6 and TNF-α, which are elevated in depression, helping to normalize hypothalamic–pituitary–adrenal axis activity and reducing hyperactivity and stress." (PMID 41562726, 2025). "Increased levels of cytokines (e.g., IL-6 and TNF-α) are often correlated with depressive symptoms, supporting the idea that inflammation is an essential component of the etiology of depression." (PMID 40305200, 2025). "Individuals with PD exhibiting more pronounced symptoms of depression, fatigue, and cognitive decline showed elevated serum concentrations of TNFα." (PMID 40333577, 2025). "In a lipopolysaccharide-induced inflammatory model of depression, escitalopram demonstrated antidepressant and anti-inflammatory effects by significantly reducing the lipopolysaccharide-induced ascend in serum TNF-α in rats." (PMID 40746874, 2025). "Clinically, TNF-α serum levels decreased when patients with depression were subjected to repetitive transcranial MS." (PMID 40014876, 2025). "Serum IL-6 and TNF-α levels are elevated in patients with depression, which can pass via the blood–brain barrier, triggering neuro-inflammation." (PMID 39856996, 2025). "Depression can arise in endotoxic shock due to a systemic inflammatory response mediated by cytokines such as TNF-α and IL-6." (PMID 41300522, 2025). "TNF-α, a key cytokine in the CNS, plays a dual role in maintaining synaptic homeostasis and contributing to the pathogenesis of depression." (PMID 40001206, 2025). "This test can be extended to assess other pro-inflammatory cytokines, such as TNF-α, IL-8, and IL-17A, which positively correlate with anxiety, depression, or cognitive impairment at various time points after the onset of AIS." (PMID 40305179, 2025). "Conversely, in males, inflammation was inversely associated with depression severity, with protective effects from regulatory mediators (IL-2, IL-4, IL-6, IL-15, LIF, TNF-α, β-NGF) against depression." (PMID 40305313, 2025). "Hesperidin (20, 50, and 100 mg/kg orally for 28 days) reduces depression-like behaviors and expression of IL-1β, IL-6, TNF-α, NLRP3, caspase-1 in the prefrontal cortex and microglia in chronic unpredictable mild stress (CUMS)-induced rats." (PMID 40703750, 2025). "The intervention led to a significant improvement in cognition and amelioration in depression, physical function, muscle mass, frailty, perceived health, and TNF-α levels." (PMID 40566334, 2025).
depression (continued). "The observation group exhibited significantly lower Bech-Rafaelsen Mania scale and Hamilton depression scale scores, as well as reduced interleukin-1 and tumor necrosis factor-alpha levels compared to the control group." (PMID 40587685, 2025). "Increased levels of inflammatory mediators, such as cytokines like IL-1β, TNF-α, and IL-6, are often seen in patients who suffer from severe depression." (PMID 40574754, 2025). "Among SSRIs, sertraline significantly reduces serum levels of IL - 1β, IL - 6, and TNF-α in adolescents with depression." (PMID 41000397, 2025). "TNF-α, a pro-inflammatory cytokine, contributes to depression severity and treatment resistance, especially under chronic stress conditions." (PMID 41584756, 2025). "With the data available, significant associations between TNF-a, IFN-γ, IL-6 and IL-10 concentrations and level of depression were found suggesting that depression is associated with inflammatory responses in the immune system in individuals with MS." (PMID 39867847, 2025). "For instance, genetic studies have linked specific polymorphisms in inflammatory pathways, such as variations in the IL-1β and TNF-α genes, to both IBD severity and susceptibility to depression." (PMID 40823034, 2025). "Chronic stress and unresolved depression induce pro-inflammatory signaling, leading to increased circulation of IL-6, TNF-α and IFN-γ, further driving malignancy, angiogenesis, and immune evasion." (PMID 40943040, 2025). "Our findings suggest that sertraline treatment can significantly affect the levels of IL-6 and TNF-α in patients with depression." (PMID 41023687, 2025). "Studies show a correlation between TNF-α and fatigue, particularly in leukemia and depression patients." (PMID 40427027, 2025). "Most present studies mainly focused on exploring the relationship of IL-1b, IL-2, IL-6, and TNF-a, with depression." (PMID 40530060, 2025). "Studies show a positive correlation between salivary TNF-α and depressive symptom severity, particularly in individuals with somatic complaints or treatment-resistant depression." (PMID 40728957, 2025). "We found multiple deregulated genes involved in pain, such as TNF, IL1B, and IL6ST, were identified as being associated with both depression and suicide." (PMID 40313396, 2025). "The model group exhibited significantly higher levels of IL-1β, IL-6, and TNF-α compared to the blank group (p < 0.01), indicating that the depression model successfully induced systemic inflammatory responses." (PMID 41464995, 2025). "Concurrently, patients with depression commonly exhibit chronic low-grade inflammation, characterized by persistently elevated pro-inflammatory cytokines [e.g., interleukin-6 (IL-6), Tumor Necrosis Factor-alpha (TNF-α)] and excessive activation of glial cells." (PMID 40641625, 2025). "Specifically, TNF-α levels decreased from 4.45 pg/mL to 2.11 pg/mL, with this change corroborated by a reduction in the Hamilton Depression Rating score compared to matched controls." (PMID 40277932, 2025). "The polarization of microglia and the level of pro-inflammatory cytokines TNF-α, IL-1β, and IL-6 have been widely used to assess neuroinflammation in Alzheimer’s disease, major depression, ASD, and ADHD." (PMID 40429903, 2025). "Another key proinflammatory cytokine involved in depression is TNF-α, produced by activated microglia, influencing neuronal function and survival." (PMID 40305200, 2025). "Inflammatory markers such as interleukin-6 (IL-6) and tumor necrosis factor-alpha (TNF-α) are consistently elevated in patients with depression." (PMID 41346637, 2025). "By inhibiting the cGAS-STING pathway, exercise reduces the expression of interferon beta-1 (IFNβ1) and other pro-inflammatory cytokines IL-6 and TNF-α, thereby decreasing the inflammatory response, improving mitochondrial function, and alleviating depression." (PMID 40699781, 2025).
depression (continued). "Elevated C-reactive protein (CRP) and Interleukin-6 (IL-6) are consistently observed with sleep disturbance and with extreme sleep durations, and meta-analytic data in depression show increases in IL-6/ Tumor Necrosis Factor-Alpha (TNF-α) and CRP." (PMID 41662130, 2025). "Inflammatory cytokines, including TNF-α, are involved in the development of anxiety and depression by triggering neuronal damage and microglial dysfunction." (PMID 40766923, 2025). "In recent years, the roles of pro-inflammatory cytokines (e.g., TNF-α, IL-1β) and anti-inflammatory cytokines (e.g., IL-4, IL-10) in the pathophysiology of depression have been increasingly clarified." (PMID 40453075, 2025). "Enhanced levels of neuroinflammatory cytokines (such as IL-1β, TNF-α, and IL-6) are observed in individuals with depression." (PMID 40703750, 2025). "Chronic activation of pro-inflammatory cytokines, including tumor necrosis factor-alpha (TNF-α), interleukin-1 beta (IL-1β), and interleukin-6 (IL-6), is observed in both PH and depression." (PMID 39941652, 2025). "Our findings revealed significantly elevated circulating levels of IL-6, IFN-γ, IL-17, TNF-α, IL-10, and IL-27 in individuals with depression compared to healthy controls." (PMID 41561993, 2025). "A third study on patients with treatment-resistant depression showed an increase in TNF-α serum levels with ketamine." (PMID 40573262, 2025). "A meta-analysis of mean differences and variability in 5166 patients and 5083 controls showed that levels of CRP, IL-3, IL-12, IL-18, sIL-2R and TNF were significantly higher in patients with depression." (PMID 40141399, 2025). "Elevated levels of proinflammatory cytokines, such as interleukin-6 (IL-6), tumor necrosis factor-alpha (TNF-α), and C-reactive protein (CRP), have been observed in subsets of patients with depression and have been associated with poor treatment outcomes." (PMID 41155383, 2025). "In adults with depression, elevated levels of IL-6 and, to a lesser extent, TNF-α and C-reactive protein (CRP) have been consistently reported." (PMID 40563330, 2025). "Elevated IL-6 and TNF-α levels, commonly observed in individuals with depression, contribute to inflammation and HPA axis activation, influencing mood regulation, neurotransmitter metabolism, and neural plasticity, thereby exacerbating depressive symptoms." (PMID 39949541, 2025). "One of the key findings of this study was the significant elevation of pro-inflammatory cytokines—interleukin-1β (IL-1β) and tumor necrosis factor-α (TNF-α)—in the depression subgroup." (PMID 40823578, 2025). "Concurrently, inflammatory cytokines like IL-1β and TNF-α induce serine phosphorylation of insulin receptor substrates, establishing a molecular bridge between inflammation, depression, and metabolic dysfunction." (PMID 40904459, 2025). "Elevated TNF-α represents a prominent inflammatory biomarker in major depression, correlating with disease severity and demonstrating partial reversibility following SSRI treatment." (PMID 41000397, 2025). "Pro-inflammatory cytokines, such as IL-6, TNF-α, and IL-1β, are among the most studied biomarkers of inflammation in depression." (PMID 40004109, 2025). "Cumulative studies have demonstrated peripheral proinflammatory markers, such as CRP, IL-6, IL-1β, and TNF-α, were significantly increased in individuals suffering from depression." (PMID 40108901, 2025). "A meta-analysis of 24 studies revealed that plasma TNF-α levels are significantly elevated in individuals with depression compared to healthy controls." (PMID 40001206, 2025). "In this study, compared to the control group, CRS mice with anxiety and depression showed significantly increased expression levels of Notch1/Hes-1, TNF-α, IL-1β, and IL-6 in the hippocampal region." (PMID 39789446, 2025). "The anti-inflammatory activity of omentin resides in its ability to downregulate the production of IL-1β, IL-6, and TNF-α, which are often involved in depression’s pathogenesis." (PMID 41375608, 2025).